SNX5 (sorting nexin 5)
Diseases named in the same sentence as SNX5 in open-access papers (continued):
Sharing a sentence is not in itself a finding about the gene and the disease.
cancer (14 papers, 2015 to 2025). A tumor composed of atypical neoplastic, often pleomorphic cells that invade other tissues. "Aberrant expression of SNX5 can contribute to tumorigenesis, invasion, and metastasis of several human cancers." (PMID 35024436, 2022). "Recently, SNX3 was also shown to bind with EGFR using biotin proximal labelling approach, and SNX5 immunoprecipitated with EGFR in Huh7—a hepatocyte-derived carcinoma cell line." (PMID 36359754, 2022). "SNX5 knockdown and knockout stopped most of the macropinocytosis in A549 cells, showed significant reduction in cancer cell proliferation, cell migration/invasion, and tumor growth." (PMID 31582910, 2019). "Interestingly, increased expression of SNX5 has been evidenced in the progress of cancer cell proliferation through EGFR-ERK1/2 signaling pathway." (PMID 35831348, 2022). "In addition, the expression levels of SNX5 were significantly increased in OSCC cancer tissues and cell lines." (PMID 36528556, 2022). "SNX5 was reported as a tumor promoter in a variety of cancers." (PMID 36528556, 2022). "Therefore, we determined the effects of overexpression or knockdown of SNX5 on the marker of potential cancer stem cell (CSC)." (PMID 35024436, 2022). "SNX5, a critical regulator in cancers, had a binding site of miRNA-127-5p in its 3′ UTR." (PMID 33982667, 2021). "A decrease in E-cadherin and ZO-1 expression by the micropinocytosis of exATP and genetic deletion of sorting nexin-5 (SNX5, a gene involved in intracellular trafficking) reduced cancer cell proliferation and metastasis." (PMID 36741002, 2023). "SNX5 is an essential factor in EGFR signaling, whose oncogenesis effect has been identified in various cancers." (PMID 34041868, 2021). "Moreover, knockout of the sorting nexin 5 (SNX5) gene (an essential gene for macropinocytosis) inhibits ATP internalization and suppresses cancer cell proliferation and cell migration in vitro and in vivo." (PMID 36750864, 2023). "In addition, exosomal circRNA 0001445 acted as a sponge for miRNA-127-5p to upregulate the expression of sorting nexin 5 (SNX5), which is a critical regulator in cancers." (PMID 36438184, 2022). "Knockout of the sorting nexin 5 (SNX5) gene (a protein very important for macropinocytosis) lowers intracellular ATP levels and inhibits cancer cell proliferation and cell migration, confirming the important role of macropinocytosis in eATP-mediated tumorigenesis and metastasis." (PMID 33212982, 2020). "Although no study revealed the roles of SNX21 in cancer, its family genes, such as SNX1, SNX5 and SNX9 were suggested to be tumor suppressor related." (PMID 31565549, 2019).
infection (12 papers, 2012 to 2023). The state of being infected such as from the introduction of a foreign agent such as serum, vaccine, antigenic substance or organism. "Loss of SNX5 increased virus replication in tissue culture and increased susceptibility of neonatal Snx5−/− mice to lethal infection by several viruses." (PMID 36288298, 2022). "Upregulation of Snx5 in PRV-infected sEVs suggest the possible role of secretory autophagy during infection of placental cells." (PMID 37781396, 2023). "In vivo experiments showed that neonatal Snx5 knockout (Snx5-/-) mice were more susceptible to lethal infection with SIN, Chikungunya virus (CHIKV), or West Nile virus (WNV) virus than their wild-type littermates (Snx5+/+)." (PMID 35898490, 2022). "Recently, a genome‐wide siRNA screening identified the endosomal protein SNX5 (sorting nexin 5) as an essential factor for virus‐induced autophagy, and knockout of Snx5 in mice enhances lethality in response to infection by several human viruses." (PMID 34459017, 2021). "This eventually revealed that IncE competes with cation-independent mannose 6-phosphate receptor (CI-M6PR) for binding to SNX5, and that the SNX5:CI-M6PR interaction is inhibited during host cell infection by C. trachomatis." (PMID 31528632, 2019). "Together with direct biochemical assays and in vivo infection assays, we demonstrate that IncE disrupts the SNX5-PX:CI-MPR interaction to alter retromer-dependent trafficking." (PMID 28252385, 2017). "SNX5 also promotes the infection of human cytomegalovirus (HCMV) through direct interaction with its tegument protein ppUL35; here the diversion of SNX5 results in a defective retrograde transport of CI‐MPR that might facilitate virus replication." (PMID 37089068, 2023). "Indeed, SNX5 colocalized with internalized Lm to a greater extent (82%) compared with SNX6 (40%), suggesting a differential role of the two proteins during infection." (PMID 29666193, 2018). "Residues required for binding to SNX5 are preserved in these IncE homologues, but whether SNX proteins are also recruited during infection by these other chlamydial species remains to be determined." (PMID 28226239, 2017). "Interestingly, the distinct effects of different sorting nexins on infection parallel the noncanonical recruitment of SNX5/6 to sites of Lm entry." (PMID 29666193, 2018).
tumor (12 papers, 2019 to 2025). "The knockout of macropinocytosis-associated SNX5 gene significantly reduces macropinocytosis, slows down tumor growth, and changes tumor morphology in nude mice." (PMID 31582910, 2019). "Additionally, we found that the higher expression of SNX5 was strongly associated with the tumor grade of OSCC patients in Oncomine database." (PMID 36528556, 2022). "The fact that expression of SNX5 is associated with tumor size and tumor thrombus in ccRCC led us to rationalize that SNX5 might be important for ccRCC tumor growth and metastasis." (PMID 35024436, 2022). "NAT10 remodeled the ac4C modification of the mRNAs of the oncogenic genes ATAD2, SOX4, and SNX5, which have been confirmed to play important roles in tumor metastasis and angiogenesis." (PMID 40301349, 2025). "Previously, our analysis identified dysregulated circRNAs in OSCC specimens, among which a circular RNA derived from the SNX5 gene (circSNX5) was significantly upregulated in tumor tissues compared to normal tissues." (PMID 39155279, 2024). "In this study, we found that SNX5 expression was downregulated and negatively correlated with tumor size, American Joint Committee on Cancer stage, tumor thrombus of inferior vena cava, and poor prognosis in human ccRCC." (PMID 35024436, 2022). "The expression of SNX5 was closely associated with tumor size, AJCC stage tumor thrombus of IVC, and prognosis." (PMID 35024436, 2022). "Our results showed that expression of SNX5 was closely associated with tumor size, American Joint Committee on Cancer (AJCC) stage, and tumor thrombus of inferior vena cava (IVC)." (PMID 35024436, 2022). "SNX5 is one of the components of the mammalian cargo-selective complex of retromer, so SNX5 exerted impact on tumor progression by directly affecting the transportation of diverse cell surface receptors or others." (PMID 35715463, 2022). "Although the knockout of SNX5 gene in tumor cells shows a reduction in cell proliferation, the cell migration and invasion abilities were largely maintained." (PMID 31582910, 2019). "This is the first time the KO of SNX5 is found to drastically affect human tumor growth in a nude mouse model." (PMID 31582910, 2019). "A forest plot highlighted key oncogenic factors such as SNX5, YBX1, TPM3, and RAB7A, which were significantly associated with poorer survival and may drive tumor progression." (PMID 41031219, 2025). "In conclusion, this study shows that SNX5 is a tumor suppressor in ccRCC." (PMID 35024436, 2022). "Mechanistically, SNX5 facilitates the internalization and inhibits the recycling of CD44 in ccRCC cells, thereby inhibiting EMT of ccRCC cells and exerting a tumor suppressor function." (PMID 35024436, 2022). "The knockout of SNX5 gene reduced macropinocytosis and thereby reduced extracellular nutrient internalization and EMT, leading to decreased tumor cells’ movement and reduced tumor shape irregularity in the KO tumors." (PMID 31582910, 2019). "The model includes seven key genes—SNX5, YBX1, GNPD1, RAB32, TPM3, ATP6V0B, and RAB7A—which may be involved in tumor growth, immune escape, and microenvironment remodeling and may serve as potential targets for therapy." (PMID 41031219, 2025). "We found that the expression level of SNX5 was highly increased in HNSC tumor tissues compared with normal tissues." (PMID 36528556, 2022). "In addition, expression of SNX5 was also downregulated in ccRCC tumor tissue compared with noncancerous tissues using the Clinical Proteomic Tumor Analysis Consortium (CPTAC) datasets." (PMID 35024436, 2022).
bacterial infection (1 paper, 2017). "Although some SNX family proteins, such as SNX3 and SNX5, have been shown to affect phagocytosis, our results suggested that SNX10 deficiency did not affect the phagocytosis of macrophages following bacterial infection." (PMID 28903313, 2017).
neurological diseases (1 paper, 2023). "Our work provides a new information on the role of SNX5 and SNX6 in the molecular regulation of retrograde membrane trafficking and vesicular membrane targeting in monoamine neurotransmission and neurological diseases." (PMID 37964759, 2023).
SNX5 also shares sentences with these, for which no sentence is quoted: Chlamydial infection (2 papers); clear cell renal cell carcinoma (2); diabetes (1); liver cancer (1); medulloblastoma (1); oral squamous cell carcinoma (1); Parkinson disease (1); stomach cancer (1); thyroid (1).